DCLK1 (doublecortin like kinase 1)
Diseases named in the same sentence as DCLK1 in open-access papers (continued):
Sharing a sentence is not in itself a finding about the gene and the disease.
colitis (21 papers, 2015 to 2025). Inflammation of the colon. "Expansion of Dclk1+ cells occurs following DSS-induced colitis and conditional recombination of the Apcfl allele in an expanded population of Dclk1+ cells leads to adenomas in the colon." (PMID 36860494, 2022). "We also provide evidence that microbial imbalance induced by an enteric pathogen synergizes with loss of crypt DCLK1 and Notch dysregulation to promote deviant or aberrant immune activation that accompanies development of colitis." (PMID 34226497, 2021). "Tuft and goblet cells play important roles in protecting the colonic epithelium from damage, as demonstrated by spontaneous colitis in Muc2−/− mice and increased susceptibility to DSS colitis in Dclk1-deficient animals." (PMID 33547321, 2021). "Thus, loss of crypt DCLK1 following inhibition of epithelial Notch signaling coincides with bacterial dysbiosis and severity of colitis." (PMID 34226497, 2021). "To establish the role of DCLK1 and its isoforms in the progression of colitis, we mated DCLK1fl/fl mice with CDX2-Cre/ERT2 mice to develop DCLK1ΔIEC mice using tamoxifen-induced Cre recombination." (PMID 40839695, 2025). "Expanding upon prior investigations emphasizing the importance of DCLK1 and its isoform in gastrointestinal function, this study investigates the role of the DCLK1 isoform (DCLK1-S) in colitis and modulation of inflammation." (PMID 40839695, 2025). "In the CR+DBZ group, denoting a more severe form of colitis, aberrant crypt architecture correlated with a decline in DCLK1 staining." (PMID 40839695, 2025). "Co-localization of DCLK1 staining with Vimentin revealed a rapid increase in Vimentin expression levels as inflammation progressed and was sustained with more severe colitis, which is in clear contrast to the E-cadherin/DCLK1 patterns previously observed." (PMID 40839695, 2025). "Latest research has demonstrated that DCLK1 acts a key function in a variety of illnesses, such as colitis." (PMID 37443105, 2023). "Through controlling mucosal immune reactions, the Notch-DCLK1 axis is vital for the establishment of murine and human colitis by modulating mucosal immune reactions." (PMID 37443105, 2023). "DCLK1 regulates inflammation in both human and murine colitis with DCLK1.2 and DCLK1.4 showing differential regulation." (PMID 38003596, 2023). "Additional evidence from induced colitis experiments in an epithelial-specific DCLK1 knockout mouse demonstrates that the DCLK1 protein expression in TCs is a key factor in their activation during the inflammatory response." (PMID 34830884, 2021). "DCLK1 is a microtubule-associated protein that marks long-lived, quiescent epithelial tuft cells in the intestine, and recent studies have revealed that deletion of DCLK1 led to worsened colitis." (PMID 35008767, 2021). "Employing human and murine models of colitis, we discovered that the two isoforms of DCLK1 are expressed differently in the epithelial vs. sub-epithelial regions of the inflamed mucosa." (PMID 34226497, 2021). "Recent studies in colon and pancreas models of inflammation demonstrate that DCLK1+ cells patrol for injury and initiate the inflammatory response to helminth infection, viral infection, colitis, and pancreatitis." (PMID 30899515, 2019). "On the other hand, PGE2/Cox2/Dclk1 axis is shown to be an important mediator of tuft cell function under bacterial-induced colitis by enhancing epithelial repair responses." (PMID 31645712, 2019). "In response to Abx treatment, we observed a significant increase in Dclk1+ cells that correlated with increased animal survival and amelioration of colitis-like symptoms." (PMID 30383855, 2018). "Similar to these results, depletion of Dclk1 + tuft cells dramatically exasperated the effects of DSS colitis." (PMID 26856877, 2016). "Moreover, immunofluorescence imaging reveals consistent findings, indicating an increase in Dclk-1 + tuft cell numbers in colitis mice treated with TSG-6." (PMID 40301757, 2025).
colitis (continued). "However, protein levels of CHGA declined, and those of Dclk1 increased in PSTi8-treated female mice compared to in PBS-treated female mice in colitis." (PMID 39684467, 2024). "Using both murine and human models of colitis, we demonstrate that loss of epithelial but not stromal DCLK1 synergizes with stromal Notch1 to regulate inflammatory processes in the colon." (PMID 34226497, 2021). "Similarly, tuft cells that express doublecortin-like kinase 1 (Dclk1) can serve as cells-of-origin for intestinal tumors in Apc knockout mice exposed to colitis-inducing agents." (PMID 33969420, 2021). "We therefore propose that, by regulating the mucosal immune responses, the Notch–DCLK1 axis may be integral to the development of murine or human colitis." (PMID 34226497, 2021). "However, a few recent studies reporting DCLK1 in colitis promoted us to test whether DCLK1 plays a role in inflammatory diseases, such as atherosclerosis." (PMID 36896602, 2023). "We therefore hypothesized that mice lacking epithelial DCLK1 when challenged with CR infection may be highly susceptible to epithelial Notch inhibition and develop severe inflammation and colitis." (PMID 34226497, 2021). "Indeed, DCLK1+ tuft cells have recently been identified as new players in colitis." (PMID 34226497, 2021). "Conversely, as colitis severity increased in the CR+DBZ group, there was a slight decrease in DCLK1 expression accompanied by an increase in FoxD3 status." (PMID 40839695, 2025). "With more severe colitis in the CR+DBZ group, we observed a rebound in FoxD3 staining concomitant with a decline in DCLK1 further indicating an inverse relationship." (PMID 40839695, 2025). "DCLK1 minimally colocalized with MMP13 in the untreated controls, but this colocalization became more prominent following DSS-induced colitis." (PMID 40839695, 2025). "This upregulation of nuclear DCLK1 in the early phase of AECII cell injury may activate the downstream signaling pathways, promoting proinflammatory cytokine production in response to virus infection and causing neutrophil activation in LPS-induced murine colitis to eliminate microbial invasion." (PMID 37996782, 2023). "DCLK1+ tuft cells which are the main producers of IL25 in the intestine had stem cell properties and played an important role in colitis and CRC initiation." (PMID 35359953, 2022). "In CR-infected Rag1−/− mice, higher levels of DCLK1 in the colonic crypts were inhibited when mice received DBZ for 10 days coincident with significant dysbiosis, barrier disruption, and colitis." (PMID 34226497, 2021). "Thus, more studies are needed to fully comprehend DCLK1 isoform-specific regulation of MMP13-driven inflammation and colitis." (PMID 40839695, 2025). "Interestingly, the ablation of doublecortin-like kinase 1 (DCLK1), a marker of tuft cells, in the colonic epithelium exacerbates colitis in mice." (PMID 32823895, 2020). "The ablation of Dclk1+ tuft cells in the colon leads to a significant reduction in epithelial proliferation, and exaggerated epithelial damage, after dextran sodium sulfate (DSS)-induced colitis." (PMID 31405140, 2019). "When intestinal epithelial cell-specific Dclk1-knockout (Dclk1ΔIEC) or Dclk1ΔIEC;Rag1−/− double knockout (DKO) mice were infected with CR and given a single dose of DBZ, they developed barrier defect and severe colitis with higher levels of stromal DCLK1-S, Ly6G, NE, and Notch1." (PMID 34226497, 2021).
gastric cancer (20 papers, 2019 to 2025). A primary or metastatic malignant neoplasm involving the stomach. "Recent studies have suggested a potential association between markers typically associated with gastric cancer stem cells, such as Lgr5 and Dclk1, and other cancer markers." (PMID 36937484, 2023). "According to the studies from whole human genome sequencing, DCLK1 is classified as top 15 putative drivers for causing gastric cancer as a result of somatic mutations." (PMID 36250024, 2022). "These correlations suggest that DCLK1-based prediction of outcome in colon and stomach cancers may be associated with stromal and immune cells in the TME." (PMID 31979136, 2020). "Therefore, Dclk1 may provide a potential target for developing new therapies for gastric cancer, as well as a diagnostic marker for identifying CSCs in gastric cancer." (PMID 36937484, 2023). "In conclusion, our results demonstrate that DCLK1 is linked with functional regulation of the tumor microenvironment and may have potential as a prognostic biomarker and adjuvant target to promote immunotherapy sensitivity in colon and gastric cancer patients." (PMID 31979136, 2020). "Cell-based assays indicated that DCLK1 is a promoting factor in gastric cancer and can promote oxaliplatin resistance in gastric cancer cells." (PMID 40963862, 2025). "We found that molecules such as ABCA6, DCLK1, and ADCYAP1 were linked to higher risk, with DCLK1 and ADCYAP1 being downregulated, while THPO and C5orf46 were upregulated in gastric cancer tissues." (PMID 41049174, 2025). "Leveraging the Cancer Genome Atlas (TCGA) dataset, we stratified gastric cancer patients into N0–N3 categories and identified a core set of molecules, including ABCA6, DCLK1, and ADCYAP1, whose expression is tightly linked to LN metastasis." (PMID 41049174, 2025). "The results proved that the proliferation of these two gastric cancer cell lines were impaired after knocking down DCLK1 compared to the Si-NC group." (PMID 40963862, 2025). "A recent study has expounded that elevation of doublecortin-like kinase 1 (DCLK1) predicts clinical prognosis in lung and gastric cancer patients, showing an association with immune infiltration." (PMID 37187527, 2023). "Dclk1 (doublecortin-like kinase 1) is a protein kinase that has been identified as a marker for cancer stem cells (CSCs) in various types of cancer, including gastric cancer." (PMID 36937484, 2023). "In cases of G.C., clinical reports frequently highlight upregulation of the cancer stemness markers CD44 and CD133, along with an increase in DCLK-1 expression within gastric carcinomas." (PMID 38136437, 2023). "DCLK1 was discovered to remodel tiny extracellular vesicles in gastric cancer, revealing its potential as an epigenetic marker." (PMID 36250024, 2022). "Using DCLK1-IN-1, the Gray, Westover, and Buchert groups demonstrated several functional properties of DCLK1 inhibition in pancreatic, colorectal, and gastric cancers, respectively." (PMID 34830884, 2021). "Overexpression of lncRNA SNHG1 can promote the expression of DCLK1 and Nothc1 in gastric cancer cells." (PMID 34422902, 2021). "Our findings again confirm that DCLK1 can be used as a prognostic biomarker for colon and gastric cancer, and extend understanding of this potential to clinically relevant subtypes." (PMID 31979136, 2020). "Based on this background, we supposed that lncRNA SNHG1 promotes EMT in gastric cancer cells via the miR-15b-regulated DCLK1/Notch1 axis." (PMID 32423385, 2020). "In summary, in colon and gastric cancers, increased DCLK1 expression correlates with poor prognosis and increased infiltration of M2 macrophages and Treg." (PMID 31979136, 2020). "Our current results demonstrate that DCLK1 expression is correlated with infiltration of multiple immune cell types in colon and gastric cancer." (PMID 31979136, 2020).
gastric cancer (continued). "High DCLK1 expression predicted the worse clinical outcomes in colon and gastric cancer patients and correlated with increased immune and stromal components." (PMID 31979136, 2020). "According to the Human Protein Atlas data, 100% of carcinoid, melanoma, colon, and breast and approximately 90% of glioma, pancreatic, and stomach cancer tissue expressed DCLK1." (PMID 31467540, 2019). "To determine whether DCLK1 affected progression in gastric cancer cells, we designed siRNA to silence DCLK1 expression in MKN-28 and HGC-27 cells." (PMID 40963862, 2025). "Furthermore, Dclk1+ cells are more resistant to chemotherapy and radiation, making Dclk1 a promising therapeutic target for gastric cancer treatment." (PMID 36937484, 2023). "In addition, whole-genome sequencing of 100 matched gastric cancer pairs identified DCLK1 as a potential new driver of gastric cancer." (PMID 36979969, 2023). "Studies have shown that Dclk1 is upregulated in gastric cancer and may play a role in the growth and spread of the disease." (PMID 36937484, 2023). "Our findings demonstrated that DCLK1 can almost predict the survival of all the specific subtypes for the first time, suggesting DCLK1 plays an important role in stomach cancer and more sophisticated classification to predict different prognoses deserves further study." (PMID 31979136, 2020). "Although there is great progress in the study of the relationship between DCLK1 and cancer, the impact of DCLK1 on the EMT process of gastric cancer remains unclear." (PMID 32423385, 2020). "Together, this data suggests that the independent prognostic prediction potential of DCLK1 in colon and stomach cancer patients may be related to alterations in the TME." (PMID 31979136, 2020). "In addition, Kaplan–Meier analyses were performed and showed that higher DCLK1 expression predicted worse DSS in every subtype stomach cancer except the MSI-Low subtype." (PMID 31979136, 2020). "Similarly, Dclk1 is upregulated in gastric cancer and may also play a role in the growth and spread of the disease." (PMID 36937484, 2023). "Doublecortin-like kinase 1 (DCLK1) marks tuft cells which are recognized as cancer-initiating cells and regulators of the type II immune response, and has been studied for its role in many cancers including colon and gastric cancers, but its role in tumor immunity remains unexplored." (PMID 31979136, 2020). "It was found that molecules like DCLK1 and ADCYAP1 were downregulated, whereas THPO and C5orf46 were upregulated in gastric cancer." (PMID 41049174, 2025). "In gastric cancer study, the enhanced EMT process by the DCLK1-mediated Notch1 pathway was observed." (PMID 36250024, 2022). "Overexpressed SNHG1 positively regulates Notch 1 and Doublecortin-like kinase 1 (DCLK1) expressions via modulation of miR-15b, inducing EMT in gastric cancer." (PMID 36229883, 2022). "MiR-15b targets DCLK1 to regulate the expression of Notch1 and inhibit the EMT process of gastric cancer cells." (PMID 34422902, 2021). "Similarly, expression of common gastric cancer stem cell markers, Lgr5, and DCLK1, was more expressed in early gastric cancer than in advanced gastric cancer, and these stem cell markers involved in cancer development and progression are involved in the early stage of gastric cancer development." (PMID 34414959, 2021). "DCLK1 is an optimal target as it represents a more specific CSC marker for colorectal, pancreatic, and possibly other cancers such as gastric cancer, esophageal cancer, breast cancer and renal carcinoma." (PMID 33348546, 2020). "In this study, we assessed DCLK1 for its role in the TME and as a prognostic marker in colon and gastric cancer using RNA-Seq data from 283 and 415 patients, respectively." (PMID 31979136, 2020). "High DCLK1 expression in tumor tissues predicted poor disease-specific survival (DSS) in both colon and stomach cancer patients (p < 0.006)." (PMID 31979136, 2020).
gastric cancer (continued). "We found that DCLK1 expression significantly correlates with both TGFB1 and CXCL12 and their receptors TGFBR1, TGFBR2, and TGFBR3, and CXCR4, respectively, in colon and stomach cancer patients." (PMID 31979136, 2020). "In summary, lncRNA SNHG1 can regulate the effects of DCLK1/Notch1 on the EMT process and cell migration in gastric cancer through miR-15b regulation, providing a novel potential target for GC treatment and also new hope for GC patients." (PMID 32423385, 2020). "TGFβ2 was negatively correlated with mRNAsi and significantly positively correlated with stemness markers (DCLK1 and CD44) in this study, so TGFβ2 may be important factor in maintaining tumor stemness and promoting tumor differentiation in gastric cancer." (PMID 35620459, 2022). "DCLK1, miR-15b, and lncRNA SNHG1 play a potential role in the occurrence of gastric cancer." (PMID 34422902, 2021). "Our findings show that low DCLK1 expression correlated with high or low CD8 + T cells predicts better survival in colon and stomach cancer patients, suggesting DCLK1 has the potential to be an adjuvant target to promote sensitivity in immunotherapy-resistant patients." (PMID 31979136, 2020).